HNRNPK (heterogeneous nuclear ribonucleoprotein K)
Diseases named in the same sentence as HNRNPK in open-access papers (continued):
Sharing a sentence is not in itself a finding about the gene and the disease.
tumor (continued). "Interestingly, the growth of tumours derived from the hnRNPK knockdown group was prominently suppressed as compared with the control group at 10 days after inoculation." (PMID 27862976, 2017). "Taken together, the role of aberrant HNRNPK expression in tumor formation and development remains unclear because of multiple cellular processes it regulates." (PMID 29262567, 2017). "Hnrnpk+/− mouse model has been proved tumor suppressive function of HNRNPK, however, transgenetic mouse model that overexpress HNRNPK will still be critical for determining the role of HNRNPK, whether it has oncogenic potential." (PMID 29262567, 2017). "The role of HNRNPK in tumor development and progression may depend on the tissue type and/or binding partners." (PMID 29262567, 2017). "Moreover, hnRNPK knockdown using the two si‐hnRNPKs significantly inhibited tumour cell growth as compared to the mock and control cells." (PMID 27862976, 2017). "Moreover, the tumours derived from the hnRNPK knockdown group had lower expression of hnRNPK and the proliferation marker Ki67 than the control group." (PMID 27862976, 2017). "To further investigate the functions of both GSK3β and hnRNPK in TRAIL-induced tumor cell apoptosis, we have either knocked down or overexpressed GSK3β or hnRNPK respectively by transient transfection of H1299 cells with corresponding siRNA or Flag-tagged expression plasmids." (PMID 26972480, 2016). "Interestingly, the expression of hnRNPK is increased in a variety of tumors and in some studies hnRNPK was reported to promote tumor metastasis." (PMID 26305187, 2015). "Thus, hnRNPK knockdown may enhance the tumor killing effect of cisplatin and promote the recovery of physiological function in mice." (PMID 39479349, 2024). "The invasion into the interior of the organoid-like structures was found to be primarily by individual tumor cells, while the quantitative results also showed that GSCs overexpressing HNRNPK (K422R) exhibited stronger invasive abilities compared to GSCs overexpressing HNRNPK (WT)." (PMID 39494331, 2024). "Notably, hnRNPK expression was significantly correlated with tumor TNM stage." (PMID 35352475, 2022). "In addition, IHC staining of CLCN3 and HNRNPK in tumor xenografts revealed that the expression of CLCN3 was decreased after HNRNPK silencing but that this reduction could be restored by CLCN3 upregulation." (PMID 36439880, 2022). "Interestingly, we also observed hnRNPK upregulation in tumour compared to normal samples." (PMID 34440306, 2021). "Moreover, HnRNPK has been characterized as a tumor suppressor in myeloid malignancy." (PMID 33330042, 2020). "Currently, the role of aberrant HNRNPK expression contributing to tumor phenotypes remains unclear." (PMID 29262567, 2017). "Although FBXW7 appears to be associated with regulation of the degradation of multiple oncogenic proteins such as c-Myc, cyclin E, and c-Jun, our findings presented in this study may suggest a putative tumor-suppressive mechanism of FBXW7 involving negative regulation of hnRNPK stability." (PMID 28423622, 2017). "By targeting several proteins such as Tap 63, Heterogeneous Nuclear Ribonucleoprotein K (HNRPK), and Programmed Cell Death Protein 4 (PDCD4), miR-21 achieved inhibition of apoptotic pathways, hence further contributing to tumor cell proliferation." (PMID 39055532, 2024). "Circular RNA FOXK2 aggravates PDAC tumor growth and metastasis by affecting PDXK and NUF2 expression through interaction with RNA binding protein YBX1 and hnRNPK." (PMID 38833016, 2024). "We established an orthotopic GBM tumor model and demonstrated that knockdown of MGCG inhibited the development of GBM; additionally, the expression of hnRNPK and ATG2A was elevated in the clinical samples of GBM with high expression of MGCG." (PMID 37460467, 2023). "CASC11 binds to hnRNPK and promotes the WNT/β-catenin pathway to induce tumor growth and metastasis in colorectal cancer." (PMID 36982162, 2023).
tumor (continued). "In order to determine the impact of HNRNPK on UOK109 and 786-O behavior, the following assays were performed: colony formation, tumor sphere formation, EdU, flow cytometry, and Transwell assays." (PMID 35897085, 2022). "Another study reported that circFOKX2 contributed to tumor progression in PDAC by sponging miR-942 and interacting with YBX1 and hnRNPK." (PMID 36008392, 2022). "We discovered that the protein levels of HNRNPK, P4HA1, and TUBA4A were significantly upregulated, while CTSL, HNRNPK, and OSBPL5 were significantly downregulated in the tumor tissues compared to those of normal tissues." (PMID 35284334, 2021). "Among these genes, the mRNA levels of ECT2, HNRNPK, P4HA1, and TUBA4A were significantly upregulated in the tumor tissues, when compared to those in normal tissues." (PMID 35284334, 2021). "Briefly, the combination of hnRNPK and FXR2 affects tumour metastasis in vivo, however, the curative mechanism need to be evaluated." (PMID 34044876, 2021). "One week after intravenous injection of tumor cells, DOX treatment was started to induce the activation of TetR, and then expression of the shRNA targeting HNRNPK was activated." (PMID 31942561, 2019). "A549 tumor cells were intravenously injected through the tail vein, and then 1 week later, DOX treatment was started to induce the downregulation of HNRNPK expression." (PMID 31942561, 2019). "Next, the hnRNPK stable knockdown or sh‐control cells were subcutaneously injected into BALB/c nude mice and the tumour growth activity was measured." (PMID 27862976, 2017). "Therefore, our data support that the HNRNPK/CLCN3 axis facilitated LUAD progression through the interaction between CAFs and tumor cells." (PMID 36439880, 2022). "To delve further into one potential function of the HNRNPK in tumor progression of NONO-TFE3 tRCC, we constructed a dCas9-based system to recruit HNRNPK to the TRAF3IP2 promoter by MS2-loop on gRNA." (PMID 35897085, 2022). "However, the mRNA levels of CTSL, HNRNPK, LRIG1, and OSBPL5 were significantly downregulated in the tumor tissues compared to those observed in normal tissues." (PMID 35284334, 2021). "Furthermore, immunohistochemical analysis of tumor tissues dissected from these mice revealed that, compared to the control group, the si‐circTUBD1 group exhibited decreased E‐cadherin expression and increased N‐cadherin, CCAR1, Ki67, and hnRNPK expression." (PMID 40130381, 2025). "Therefore, the hnRNPK-regulated tumor growth is specific to cancer cells but not to the normal cells." (PMID 35875075, 2022). "A previous study demonstrated that circFOKX2 not only interacts with YBX1 and hnRNPK to elevate the expression of the oncogenes NUF2 and PDXK but also functions as a sponge for miR-942 to upregulate the expression of ANK1, GDNF, and PAX6, which contribute to tumor progression in PDAC." (PMID 34419070, 2021). "Furthermore, the recruitment of the SCAT7/hnRNPK/YBX1 RNP complex at the promoter regions of FGFR2 and FGFR3 promotes transcriptional activation of FGF/FGFR and its downstream PI3K/AKT and MAPK pathways, leading to sustained cell proliferation and tumor development." (PMID 30658384, 2019). "The reason for the differences in expression and functions of hnRNPK in different cell systems is not understood; however, the function of hnRNPK is dependent on its subcellular localization, i.e. cytoplasmic vs. nuclear, and tyrosine phosphorylation which may be cell-and tumor dependent." (PMID 26305187, 2015). "Moreover, knockdown of hnRNPK or FXR1 but not FXR2 increased the tumour growth of mouse model with MCF7 cells, whereas double knockdown or triple knockdown of the RNA-binding proteins significantly decreased primary tumour growth." (PMID 34044876, 2021).
cancer (123 papers, 2006 to 2025). A tumor composed of atypical neoplastic, often pleomorphic cells that invade other tissues. "Some RNPs such as RBM3, IMP3, and CUG-BP1 facilitate the formation of drug resistance 22 while heterogeneous nuclear ribonucleoprotein K has been associated with cancer procession and high risk of metastasis." (PMID 37324186, 2023). "While c-Myc is not the only target, it represents a key oncogenic driver and potential therapeutic target in cancers with loss of Fbxo4 and accumulation of cytoplasmic hnRNPK." (PMID 36329064, 2022). "Loss of SCFFbxo4 results in unrestricted hnRNPK activity, overexpression pro-oncogenic factors (eg. c-Myc), increased proliferation, invasion and motility leading to an aggressive cancer phenotype." (PMID 36329064, 2022). "Cytoplasmic accumulation of RNA binding protein, hnRNPK in cancer cells is associated with poor prognosis." (PMID 36329064, 2022). "As a multifunctional RNA-binding protein, heterogeneous nuclear ribonucleoprotein K (hnRNPK) is closely associated with cancer progression in various types of cancers." (PMID 33731671, 2021). "Taken together, these results support a novel pan‐cancer mechanism for CAV1‐driven exosomal release of hnRNPK and associated miRNA in metastasis, which is modulated by the membrane lipid environment." (PMID 33931969, 2021). "Heterogeneous nuclear ribonucleoprotein K (hnRNPK) is an important cancer-related RNA- and DNA-binding protein associated with poor prognosis in BC, while EZH2 is a histone methyltransferase that acts as an oncogene important for self-renewal." (PMID 32756406, 2020). "Increased hnRNPK expression is associated with malignant tumor and its aberrant cytoplasmic expression is associated with metastasis in several tumors." (PMID 31492158, 2019). "HnRNPK has been implicated in several biological functions crucial for cancer development 30, including proliferation 15, 31, 32, metastases 19, 20, angiogenesis 33 and neuroendocrine differentiation." (PMID 27862976, 2017). "In particular, HNRNPK was reported to be associated with cancer development in 177 papers." (PMID 36681772, 2023). "While HNRNPK primarily resides in the nucleus, it impacts all steps of gene expression and a cytoplasmic pool of HNRNPK has been linked to metastasis and poor prognosis in cancer." (PMID 37592256, 2023). "Similarly, KO mouse model of cancer-testis lncRNA in hepatocellular carcinoma (lnc-CTHCC) revealed its pro-oncogenic properties via association with hnRNPK and YAP1 transcriptional activation." (PMID 36230680, 2022). "Cancers of the esophagus also exhibit hnRNPK mislocalization and SCFFbxo4/αB-Crystallin loss." (PMID 36329064, 2022). "Interestingly, some NDD hnRNPs have already been implicated in cell division through cancer studies, including hnRNPD, hnRNPK, SYNCRIP, and hnRNPU." (PMID 33874999, 2021). "The invasive ability was reduced by hnRNPK knockdown; conversely, overexpression of hnRNPK enhanced the invasive ability, indicating that hnRNPK is closely associated with the invasiveness of cancer cells." (PMID 33731671, 2021). "Moreover, this protein-protein interaction network also indicated that HNRNPK was physically interacted with many other critical cancer associated genes such as EGFR, CD81 and AURKA." (PMID 29262567, 2017). "Heterogeneous nuclear ribonucleoprotein K (hnRNP-K) is an RNA and DNA binding protein that regulates transcription and translation, and has been implicated in the pathology of several types of cancer." (PMID 20865152, 2010). "Notably, a supporting role of hnRNPK in cancer progression has been implied due to its elevated expression in various cancers and its positive association with aggressive metastasis, poor prognosis, and a cancer stem cell phenotype." (PMID 34575922, 2021).
cancer (continued). "Named after the human heterogeneous nuclear ribonucleoprotein K (hnRNP K), the KH domain is an ancient RNA-binding module present in proteins whose disruption causes important developmental alterations in animals, including human syndromes as fragile-X, metastasis and cancer progression." (PMID 25658099, 2015). "This work establishes a novel therapeutic strategy to inhibit MYC translation mediated by hnRNPK, offering a translationally targeted approach to cancer therapy." (PMID 40943063, 2025). "We recently demonstrated that RNA-binding domains of hnRNPU, RBM39 and hnRNPK inhibit the survival of a range of cancer cells." (PMID 38349913, 2024). "Several studies have shown the implication of the HNRNPK protein in cancer by interacting with other proteins and signaling pathways such as the WNT pathway." (PMID 39409902, 2024). "Lnc-FAM84B-4 interacts with HNRNPK, promoting cancer progression by suppressing the expression of the MAPK phosphatase DUSP1." (PMID 38238853, 2024). "In particular, high expression of hnRNPK is observed in several cancers, and its promoting effect on cell metastasis and its significance in poor prognosis implicate hnRNPK as a cancer promotor." (PMID 37426488, 2023). "A computational pipeline and webserver identify regulators of RNA-binding proteins (RBPs) at single-cell resolution and are applied to determine the role of RBP HNRNPK in cancer." (PMID 36681772, 2023). "Functional assays performed in cancer cells reveal that HNRNPK promotes cancer cell proliferation, migration, and invasion in vitro and in vivo." (PMID 36681772, 2023). "In cancer, hnRNPK binds to the promoter regions of MYC (MYC proto-oncogene) and SRC (SRC proto-oncogene) to elevate their transcription or binds to their mRNAs to control translation." (PMID 36735291, 2023). "PLK1 expression has been shown to be positively regulated by heterogeneous nuclear ribonucleoprotein K (hnRNPK) in various cancer cell lines." (PMID 36611980, 2023). "It was previously shown that shuttling of HNRNPK to the cytoplasm promotes cell proliferation and cancer metastasis." (PMID 37592256, 2023). "lncRNA 91H has been shown to promote cancer migration and invasion by regulating the expression of heterogeneous nuclear ribonucleoprotein K (HNRNPK)." (PMID 37007117, 2023). "HNRNPK regulates a wide range of BPs and disease pathogenesis, which is central to many cellular events, including long noncoding RNA (lncRNA) regulation, cancer development, and bone homeostasis." (PMID 36052164, 2022). "Abnormal cytoplasmic accumulation of hnRNPK occurs frequently in cancer and is clinically unfavorable in various cancers." (PMID 36329064, 2022). "Here the authors show that SCFFbxo4 E3 ubiquitin ligase-mediated polyubiquitylation of hnRNPK restricts c-Myc translation and limits cancer progression." (PMID 36329064, 2022). "The increased appearance of dsRNA signals, as well as co-localization of IER3 and IER3-AS1 transcripts in multiple cancer cell lines following hnRNPK KD, point towards a critical role of HnRNPK in regulating global RNA–RNA interactions." (PMID 36038571, 2022). "While many retrospective studies focus on the modest increase in total hnRNPK that occurs in cancer, this modest increase is likely secondary to the role of dysregulated cytoplasmic hnRNPK." (PMID 36329064, 2022). "By contrast in cancer cells, hnRNPK accumulates in the cytoplasm arguing for gain of cytoplasmic function in cancer." (PMID 36329064, 2022). "We were next interested in investigating the cancer-specific hallmarks of hnRNPK KD cells where both IER3 and IER3-AS1 were upregulated." (PMID 36038571, 2022). "Currently, eight hnRNPs members (hnRNPA1, hnRNPA2B1, hnRNPC, hnRNPD, hnRNPF, hnRNPK, hnRNPR, and hnRNPU) seem to be more relevant to cancer development, according to reported literature." (PMID 35875075, 2022).
cancer (continued). "Notably, increased localization of hnRNPK to the cytoplasm in cancers has been associated with poor prognosis, suggesting that cytoplasmic functions of hnRNPK may be tumorigenic, thus highlighting an unappreciated potential layer of hnRNPK regulation." (PMID 36329064, 2022). "We also noted a significant shift of hnRNPK to the cytoplasm, perhaps reflecting an indirect consequence of increased function in translating ribosomes observed in cancer cells." (PMID 36329064, 2022). "Among the RBPs that interact with CRLM1, heterogeneous nuclear ribonucleoprotein K (hnRNPK) has been investigated for decades as a DNA-binding transactivator that recruits transcription factors that promote cancer development and metastasis." (PMID 35907898, 2022). "In this study, we sought to identify hnRNPK-regulated long intergenic non-coding RNAs (lincRNAs) that play a critical role in the regulation of cancer malignancy." (PMID 33731671, 2021). "Taken together, the hnRNPK/LINC00263/miR-147a/CAPN2 axis identified in this study represents a promising target for the treatment of human cancer." (PMID 33731671, 2021). "Pathologically, HnRNPK proteins are frequently overexpressed and clinically correlated with poor prognosis in various types of human cancers and are therefore pursued as attractive therapeutic targets for select patients." (PMID 34857003, 2021). "hnRNPK is predominantly located in the nucleus in normal cells but has been reported to translocate to the cytoplasm in some cancer cells." (PMID 33931969, 2021). "Collectively, we demonstrate that hnRNPK-regulated LINC00263 plays an important role in cancer malignancy by acting as a miR-147a decoy and thus upregulating CAPN2." (PMID 33731671, 2021). "HNRNPK is an RNA‐binding protein that is localized both in the cytoplasm and nucleus, and it has been shown to regulate the translation of oncogenes in cancer cells." (PMID 33634993, 2021). "The hnRNPK was reported to function as a DNA- and RNA-binding protein and to regulate a large number of biological processes and cancer pathogenesis." (PMID 34452628, 2021). "Since LINC00263 showed the most significant effect on the metastatic potential (data not shown), we chose to investigate its role in the control of cancer malignancy through hnRNPK." (PMID 33731671, 2021). "Next, the role of hnRNPK/LINC00263/miR-147a in the regulation of CAPN2 expression was verified in various cancer cells including DLD1, LoVo, A375, T98G, and A172 cells." (PMID 33731671, 2021). "We previously reported that hnRNPK regulates the proliferation of cancer cells by targeting polo-like kinase 1 (PLK1) and heme oxygenase-1 (HO-1)." (PMID 33731671, 2021). "Our findings indicated that FAM83H‐AS1 regulates downstream target genes that rely on HNRNPK, which is a multifunctional protein that plays important roles in cancer cells." (PMID 33634993, 2021). "Taken together, our data suggest that hnRNPK/LINC00263/miR-147a/CAPN2 represents a promising target for the development of cancer therapeutics." (PMID 33731671, 2021). "On the other hand, RK-33 treatment provides a feasible strategy for selectively promoting the DDX3 interaction with unmethylated hnRNPK in cancer cells." (PMID 34575922, 2021). "An example of a cancer-associated lncRNA that contains a SIRLOIN and is retained in the nucleus by hnRNPK is MALAT1." (PMID 32340118, 2020). "Numerous studies have observed oncogenic effects as well as a prognostic relevance of hnRNPK in different types of cancer, like breast, colorectal, and gastric cancer, where its overall levels are increased and it is aberrantly localized in the cytoplasm." (PMID 32340118, 2020).